DKK1 (dickkopf Wnt signaling pathway inhibitor 1)
Diseases named in the same sentence as DKK1 in open-access papers (continued):
Sharing a sentence is not in itself a finding about the gene and the disease.
prostate carcinoma (continued). "DKK-1 tissue expression was assessed in the prostate cancer TMA." (PMID 25182503, 2014). "Indeed, DKK-1-overexpressing prostate cancer cells were recently reported to have an increased subcutaneous tumor mass upon ectopic transplantation and a higher incidence of bone metastases after intracardiac injection." (PMID 24528599, 2014). "As prostate cancer progresses DKK1 expression declines, particularly in advanced bone metastases." (PMID 22325146, 2012). "In addition, our finding that DKK1 treatment significantly inhibits prostate cancer cell growth and migration reinforces this notion." (PMID 18478098, 2008). "Moreover, Dickkopf1 (DKK1), a Wnt pathway inhibitor, significantly inhibited prostate cancer cell growth and migration." (PMID 18478098, 2008). "Moreover, addition of a Wnt pathway inhibitor, Dickkopf 1 (DKK1), into the culture medium significantly inhibited prostate cancer cell growth and migration." (PMID 18478098, 2008). "It is suggested that tumor establishment necessitates the initial upregulation of DKK1, while a reduction in DKK1 during bone metastasis can lead to an increase in WNT expression, resulting in osteoblastic metastases that are traditionally associated with prostate cancer." (PMID 40002869, 2025). "However, the downstream genes and signaling pathways of DKK1 in prostate cancer are still unknown, which are also quite intriguing issues." (PMID 34697293, 2021). "To date, the regulatory role of DKK-1 by p38 MAPK in prostate cancer remains unknown." (PMID 26913608, 2016). "The prognostic role of DKK-1 expression in prostate cancer remains unclear." (PMID 25182503, 2014). "In prostate cancer cells, ovarian cancer cells, and osteosarcoma, JNK signaling is activated by DKK1 via a β-catenin-independent pathway and promotes cell invasion or tumor growth." (PMID 40394415, 2025). "Screening of a panel of human epithelial cancer cell lines revealed that the highest DKK1 and IL1B mRNA expression coincided in PC3 prostate cancer cells." (PMID 36539532, 2022). "Consistently, reduction of DKK1 expression significantly restores ZBTB38-mediated suppression of migration and proliferation of prostate cancer cell lines." (PMID 34697293, 2021). "ZBTB38 binds DKK1 (Dickkopf WNT signaling pathway inhibitor 1) locus and promotes DKK1 expression in prostate cancer cell lines." (PMID 34697293, 2021). "DKK-1 mRNA expression and protein secretion were assessed in PC3, MDA-PCa-2b and C4-2B prostate cancer cells lines." (PMID 26913608, 2016). "A prostate cancer tissue microarray (n = 400) was stained for DKK-1 and DKK-1 serum levels were measured in 80 patients with prostate cancer." (PMID 25182503, 2014). "Wnt-3a and Wnt-5a administration or knockdown of DKK-1 induced BMP-4 and 6 expression and promoter activation in prostate cancer cells." (PMID 22325146, 2012). "Recent DKK1 studies have reported that observed tumor suppression is independent of canonical Wnt signaling in prostate cancer." (PMID 40394415, 2025). "Sclerostin overexpression, but not DKK-1 overexpression, in prostate cancer cells decreased metastasis and migration of prostate cells." (PMID 37174109, 2023). "Our results suggest the novel role of DKK1 in prostate cancer, which could serve as the direct downstream of ZBTB38 in regulating prostate cancer cells proliferation and migration." (PMID 34697293, 2021). "Taken together, our results indicate that ZBTB38 could repress cell migration and proliferation in prostate cancer via promoting DKK1 expression, and also provide evidence supporting ZBTB38 as a potential prognosis marker for prostate cancer." (PMID 34697293, 2021). "Whereas in prostate cancer RLX promotes tumor progression via its effects on the protocadherin PCDHY18, the effects we described are mediated, at least in part, by increased expression of Wnt1 and reduced expression of Dkk1." (PMID 31811156, 2019).
prostate carcinoma (continued). "An important observation that warrants discussion is that inhibiting the expression or activity of p38 does not reduce DKK-1 expression and secretion down to the levels first observed in the non-osteolytic prostate cancer cell lines." (PMID 26913608, 2016). "The specific aims of this study were to determine if p38 regulates DKK-1 in prostate cancer and to assess if targeting p38 MAPK may have positive effects against DKK-1-inhibited osteoblastogenesis." (PMID 26913608, 2016). "DKK-1 tissue expression was significantly increased in prostate cancer compared to benign disease, but was not correlated with survival." (PMID 25182503, 2014). "Up-regulation of the WNT-family ligand WNT1 in prostate cancer cells and a decrease in the serum of the WNT antagonist dikkopf-1 (DKK1) expression has been reported in patients with advanced metastatic prostate carcinoma and is associated with osteoblastic lesions." (PMID 24069383, 2013). "Treatment of prostate cancer cells with Wnt3A CM or purified recombinant Wnt3A protein significantly enhanced cell growth and migration, while treatment of prostate cancer cells with the LRP6 antagonist Dkk1 significantly inhibited cell growth and migration." (PMID 23469146, 2013). "Consistent with our result, Forget MA and co-workers had also observed DKK1 in two hormone-independent prostate cancer lines (DU45 and PC3) and hormone receptor-negative breast tumor but not in a hormone-dependent tumor (LNCaP)." (PMID 22649545, 2012). "In fact, we observed DKK1 in two hormone-independent prostate cancer lines (DU45 and PC3) but not in a hormone-dependent tumour (LNCaP)." (PMID 17245340, 2007). "In MM cell lines, which all lack detectable levels of DKK1 protein, the DKK1 transcript was either undetectable (UM-1, RPMI 8226 and OPM-1), or weakly expressed (XG-1, L363 and LME-1) in comparison to the DKK1 expression in the (positive control) prostate cancer cell line PC-3." (PMID 22363428, 2012). "In prostate cancer cells, ovarian cancer cells, and osteosarcoma, JNK signaling was activated by DKK1; in these cases, β-catenin levels were not affected, and promotion of cell invasion or tumor growth was observed." (PMID 35355709, 2022). "ET-1 is known to contribute to osteoblastic progression of prostate cancer cells by stimulating OB proliferation through the negative regulation of the inhibitor of the Wnt signaling, DKK1 which may explain, at least in part, the decrease of DKK1 observed in PC3c cells." (PMID 24069383, 2013). "Furthermore, tissue expression in human prostate cancer revealed a correlation between p38 MAPK and DKK-1 expression with higher expression in tumor compared with normal tissues." (PMID 26913608, 2016). "Although the increases in DKK-1 mRNA expression are not to the same level of those observed in the untreated PC3 cells, they are indicative of a role of p38 signaling in defining the osteotropic signature of prostate cancer cells." (PMID 26913608, 2016).
colorectal cancer (56 papers, 2011 to 2026). A primary or metastatic malignant neoplasm that affects the colon or rectum. "In deficient mismatch repair colorectal cancer, DKK1 can also attenuate the efficacy of immunotherapy by suppressing CD8 + T cells." (PMID 37907850, 2023). "In colorectal cancer silenced DKK1 expression is tightly associated with microsatellite instability of tumor subtypes." (PMID 22815877, 2012). "Interestingly, cytoplasmic ASPN have been found to promote cell migration and indicate a poor prognosis in colorectal cancer, and elevated DKK1 expression is associated with recurrence and impairs the response to PD-1 blockade in dMMR CRC, while both of which are down regulated in IVE group." (PMID 34438367, 2021). "Loss of DKK-1 has been associated with progression of certain types of cancers, such as colorectal carcinoma (CRC)." (PMID 24250816, 2013). "Vitamin D also exerts an anti-cancer effect in cancers such as colorectal cancer by increasing the secretion of the Wnt inhibitor DKK-1, further inhibiting the abnormal activation of the Wnt signaling pathway." (PMID 40705722, 2025). "Our investigation identified DKK1 as a target significantly downregulated by DCC-2036 in colorectal carcinoma." (PMID 39788945, 2025). "Recent research in colorectal cancer has shown that, due to mismatch repair defects, DKK1 can inactivate CD8+T lymphocytes, thereby inhibiting the tumor response to PD-1 blockade therapy." (PMID 38376441, 2024). "Upregulated expression of DKK1 in colorectal cancer can inhibit CD8+ T cells through the GSK3β–E2F1–T‐BET pathway and promote malignant progression of cancer cells." (PMID 38525111, 2024). "Although Wnt signaling, including DKK1 and the peritumoral microenvironment, has been studied for many years in colorectal cancer, there are still some unexplored areas, and further studies are needed to elucidate the pathogenesis." (PMID 38334454, 2024). "DKK1 located in the nucleus of human colorectal cancer cells involved in cancer-related target gene transcription." (PMID 34093545, 2021). "In contrast, some studies have shown that DKK-1 expression is downregulated in colorectal cancer, brain tumor, and papillary thyroid cancer." (PMID 33921232, 2021). "This possibility is supported by findings, which showed that knock down of CSN5, an enzymatic component of the COP9 signalosome (CSN) that is overexpressed in many cancers, results in transcriptional derepression of DKK1 in colorectal cancer cells." (PMID 33462997, 2021). "It has been shown that the circulating DKK-1 levels were decreased in patients with gastric cancer, colorectal cancer, ovarian cancer, and cervical adenocarcinoma." (PMID 34259818, 2021). "Meanwhile, genistein has been reported to induce DKK1 expression by the acetylation of histone H3 in the DKK1 promoter region in colorectal cancer." (PMID 33420361, 2021). "LSD1 was demonstrated to activate the Wnt/β-catenin signaling pathway by down-regulating the pathway antagonist DKK1 in colorectal cancer cells." (PMID 27894074, 2017). "A previous study has shown that miR-372 promotes tumor cell proliferation and invasion by modulating DKK1 levels in colorectal cancer." (PMID 26673619, 2016). "Similar inhibition of DKK-1 has been observed in colorectal cancer, which results from the epigenetic modification of the DKK1 promoter." (PMID 24742667, 2014). "DKK1 has strong antiproliferative effects in colorectal cancer cell lines and dramatically reduces tumor burden in mouse xenografts." (PMID 23922913, 2013). "In particular, this study is among the first to link genistein-mediated epigenetic modifications of DKK1 to the anticancer properties of genistein in colorectal cancer." (PMID 22815877, 2012). "It is reported that the tumor suppressing capacity of DKK1 is repressed by the hypermethylation of its promoter in the advanced stages of colorectal cancer." (PMID 22815877, 2012).
colorectal cancer (continued). "Moreover, in colorectal cancer with impaired mismatch repair, inhibition of DKK1 improved the response to anti-PD-1 therapy by enhancing CD8+ T cell proliferation and function." (PMID 39795613, 2025). "Serum DKK1 levels were measured in patients with colorectal cancer and adenoma." (PMID 38334454, 2024). "CSN5 may regulate the stability of DKK1 by the de-neddylation of Cullin-RING-ligase, while DKK1 influences the development of colorectal cancer by regulating the wnt/β-catenin pathway." (PMID 37777749, 2023). "However, DKK1 is under-expressed in gastric cancer and colorectal cancer, in which DKK1 is regulated by miR-493 and epigenetic silencing, respectively." (PMID 36447119, 2023). "Furthermore, in our previous studies about colorectal cancer, Andro reversed 5-FU resistance through suppression of DKK1 and β-catenin/Wnt-signaling." (PMID 36672630, 2023). "In addition, the EYA4 gene has also been identified as a promising tumor suppressor gene for colorectal cancer since it controls DKK1 upregulation and blocks the Wnt signaling pathway." (PMID 37156847, 2023). "Indeed, the Wnt/β-catenin pathway is constitutively active in most colorectal cancers, where the loss of function mutation and/or epigenetic silencing of negative regulators like APC, AXIN2, DKK1, or SFRP2 are common facts." (PMID 34063173, 2021). "We also point out other mechanisms here that may contribute to DKK1 and DKK3 gene (and consequently DKK1 and DKK3 protein) silencing, such as the mutational burden and various miRNAs, as recently shown in a case of melanoma and colorectal cancer." (PMID 34064046, 2021). "To validate the effects of JIB-04 on the mRNA expression of β-catenin target genes, we measured the mRNA levels of CSC-associated genes (CD44, LGR5, DKK1, ALDH1A3, ALDH1B1, CD24, and SOX4) by qRT-PCR in three different colorectal cancer cell lines after treament with JIB-04." (PMID 29700375, 2018). "In colorectal cancer, decreased DKK1 expression is observed." (PMID 23922913, 2013). "Inactivation or down-regulation of DKK1 can lead to various cancers, including colorectal cancer." (PMID 23922913, 2013). "However, the influence of DKK1 on colorectal cancer (CRC) liver oligometastases (CRCLOM) remains unclear." (PMID 31830954, 2019). "Here, our study indicated that DKK1 could also worsen immune status in colorectal cancer." (PMID 31830954, 2019). "We found that TSGs (e.g., DKK1 and GAS5) in colorectal cancer with hypermethylated promotors were re-activated and two oncogenes (i.e., EREG and MALAT1) were down-regulated upon 5-AZA-CdR treatment." (PMID 36882403, 2023). "In summary, our findings demonstrate a novel location of DKK-1 within the cell nucleus and support a role of nuclear DKK-1 as a predictive biomarker of chemoresistance in colorectal cancer." (PMID 25788273, 2015). "We then selected the 4 colorectal cancer-related genes ADM, DKK1, HAS3 and SMURF2 for quantitative real-time PCR verification." (PMID 23922913, 2013). "Notably, genes such as DKK1, GZMB, THBS1, and CCL5—recognized for their key contributions to colorectal cancer prognosis—have been incorporated into several existing prognostic models." (PMID 40670378, 2025). "The interaction between DKK1 and CKAP4 activates the PI3K/AKT signaling pathway, promoting cancer cell proliferation and metastasis in various GI malignancies, including esophageal, gastric, pancreatic, and colorectal cancers." (PMID 41149482, 2025). "Nevertheless, some reports indicate that serum DKK1 levels are elevated in patients with advanced colorectal cancer, whereas others report no elevation." (PMID 38334454, 2024).
gastric cancer (43 papers, 2012 to 2025). A primary or metastatic malignant neoplasm involving the stomach. "Another target includes Dickkopf-related protein (DKK1) for which elevated expression is associated with worsened survival in gastric cancer, increased M2 macrophages, and an immunosuppressive microenvironment." (PMID 40676191, 2025). "Similarly, another study in serum from patients with gastric cancer had high levels of DKK1 being associated with poorer overall survival." (PMID 39936971, 2025). "In gastric cancer, the DKK1/CKPA4/Akt axis causes immune suppression in macrophages." (PMID 41149482, 2025). "From the meta-analysis evaluating the relationship of DKK1 overexpression and prognosis of patients with gastric cancer, DKK1 was defined to be a prognostic marker with its association to vascular and lymphatic invasion, distant metastasis and low overall survival." (PMID 34093545, 2021). "After identifying these prognostic genes, including CPZ, CTHRC1, DKK1, EGF, and GPC3, we will explore their specific impact on gastric cancer progression, as well as the molecular mechanisms underlying it, particularly the CPZ." (PMID 40296906, 2025). "Research has also identified significant roles for porcupine (PORCN) and DKK1 in GI cancers, particularly esophageal and gastric cancers, emphasizing their potential as therapeutic targets." (PMID 39936971, 2025). "This idea is further supported by the evaluation of NKG2D-CAR T cells in gastric cancer, whereby DKK1 suppressed NKG2D ligands, reducing NKG2D-based recognition." (PMID 39885132, 2025). "Elevated expression of DKK1 correlates with a poor prognosis in a range of cancers, including patients with esophageal and gastric cancer." (PMID 39936971, 2025). "miR-493-3p has been reported to inhibit growth of gastric cancer cells via downregulation of DKK1; nevertheless, the role and relationships of miR-493-3p and DKK1 in NB is rarely explored." (PMID 40804038, 2025). "A gastric cancer-related study found that tumor DKK1 expression was closely related to poor survival rate and suppressive tumor immune microenvironment in gastric cancer patients." (PMID 39107271, 2024). "Next, we also identified that DKK1 is highly expressed in CDDP-resistant gastric cancer cell lines, supporting the notion that DKK1 is a necessary regulator of CDDP resistance." (PMID 37835450, 2023). "DKK1 has also been connected to the stimulation of several signaling pathways in gastric cancer cells that enhance tumor formation." (PMID 36762306, 2023). "According to these findings, propofol-induced enhanced production of miR-493-3p should reduce the DKK1 expression in gastric cancer cells." (PMID 36762306, 2023). "In this study, we found that DKK1 was highly expressed in gastric cancer patients and cisplatin (CDDP)-resistant cell lines." (PMID 37835450, 2023). "DKK1 is a cell surface protein that is significantly expressed in a number of human malignancies, including breast, lung, rectal, and gastric cancers." (PMID 36762306, 2023). "DKK1 has also been demonstrated to increase the activity of Wnt/-catenin pathway in gastric cancer cells in prior investigation, suggesting that propofol inhibited Wnt/β-catenin pathway." (PMID 36762306, 2023). "Here, we found that Dickkopf-related protein 1 (DKK1) is highly expressed in gastric cancer and related to poor prognosis in gastric cancer patients through public database mining." (PMID 37835450, 2023). "The isoproterenol-mediated expression of miR-493-3p downregulated the expression level of DKK1, and miR-493-3p was found to stop the cell cycle of gastric cancer cells at the G1 phase by inhibiting DKK1." (PMID 36762306, 2023). "Expression of DKK1 in both serum and tissue levels has been reported to be a biomarker in diagnosis and predicting survival and tumor recurrence in stomach cancer." (PMID 35677557, 2022).